KRAS (KRas proto-oncogene, GTPase)
Diseases named in the same sentence as KRAS in open-access papers (continued):
Sharing a sentence is not in itself a finding about the gene and the disease.
melanoma (continued). "Activating mutations in KRAS for example are present in ∼90% of pancreatic cancers, ∼20% of CRC and ∼35% of NSCLC with B-RAF mutations present in ∼20–60% of melanomas, 35–70% of papillary thyroid and ∼12% of CRC." (PMID 22343622, 2012). "Documented sensitivity of melanoma cells to PLX4720, a selective BRAFV600E inhibitor, is based on the presence of mutant BRAFV600E alone, while wt-BRAF or mutated KRAS result in cell proliferation." (PMID 21738740, 2011). "In non-melanoma systems, chronic treatment with the MEK inhibitor CI-1040 leads to resistance associated with increased KRAS and MEK expression." (PMID 20531415, 2010). "Somatic mutations of NRAS, KRAS, and HRAS occur in 20–25, 2–3, and 2% of melanomas respectively." (PMID 41492362, 2026). "Point mutations or gene fusions in other genes (e.g., mutations in BRAF, KRAS, APC, and MET genes, or gene fusions in ZEB2‐ALK and SOX5‐RAF1 genes) may be associated with melanoma proliferation or melanoma progression in satellite nevi or LCMN." (PMID 41474606, 2026). "Finally, we evaluated the utility of Fluor-HPLC for assessing KRAS activation status in vivo using a syngeneic metastatic B16F10 mouse melanoma model in C57BL/6 mice." (PMID 40286847, 2025). "Future studies should explore these alternative mechanisms of KRAS pathway activation in melanoma subtypes lacking direct KRAS mutations." (PMID 40607411, 2025). "Nonetheless, subsets of melanomas appear to engage the KRAS signaling cascade in ways that may synergize or converge with these established oncogenic pathways." (PMID 40607411, 2025). "The integrative analyses described herein have provided evidence suggesting that KRAS-related processes could underpin tumor progression, modulate immune cell infiltration, and confer distinctive biological properties on melanoma cells." (PMID 40607411, 2025). "The three-gene KRAS-Macrophage Prognostic Associated Gene (KMPAG) signature, encompassing CLEC4A, CXCL10, and LAT2, emerges as a robust prognostic tool that correlates with distinct clinical and immunological phenotypes in melanoma cohorts." (PMID 40607411, 2025). "KRAS has been reported to be a potential driver gene for melanoma BrM." (PMID 39819494, 2025). "The present investigation sought to integrate diverse transcriptomic datasets, including single-cell RNA sequencing and bulk gene expression profiling, to elucidate the role of KRAS-related signaling in melanoma and examine how macrophage phenotypes contribute to clinical outcomes." (PMID 40607411, 2025). "Naporafenib, a RAF dimer selective inhibitor, in combination with the MEK inhibitor trametinib or in combination with the ERK inhibitor LTT462, is being explored in a clinical trial for its efficacy in advanced metastatic KRAS- or BRAF-mutant NSCLC or in NRAS-mutant melanoma (NCT02974725)." (PMID 38731852, 2024). "We also tested EGFR exon 19 (Del19 EGFR) deletions and KRAS Q61 mutations, and neither of these deregulations were found in the healthy skin, benign nevi, or melanoma samples." (PMID 38396984, 2024). "Melanoma patients were predicted to be the most resistant cancer type to KRAS dependency, regardless of KRAS mutation status." (PMID 37141389, 2023). "Because NRAS Q61K, KRAS G13D, and MEK1 Q56P mutations are associated with BRAF inhibitor resistance in BRAF V600E melanoma, we first tested each A375 model cell line for resistance to the FDA-approved BRAF inhibitor compounds dabrafenib and vemurafenib in 2D tissue culture." (PMID 36358868, 2022). "In addition, amplifications at EGFR, BRAF V600E, NRAS and KRAS loci, mutations of NRAS, KRAS and MAP2K1, and PTEN loss are often observed in resistant lesions of melanoma and CRC patients with treatment of combined RAF targeted therapies 85-87." (PMID 35966590, 2022). "Additionally, RAS mutations have been described in two canine cutaneous melanomas (one KRAS and one NRAS) and in three melanomas of the digits (two KRAS and one NRAS)." (PMID 35202309, 2022).
melanoma (continued). "Additionally, the specificity of mutations in melanoma for NRAS compared to HRAS and KRAS is noteworthy, thinking that all three isoforms proceed in GIMM and melanoma-related short-term cultures." (PMID 36551688, 2022). "Analysis of melanoma patients who developed BRAF inhibitor resistance revealed increased mitogen-activated protein kinase signaling from either development of NRAS and KRAS mutations in progressive tumors, or through 2- to 15-fold increase in BRAF mRNA compared with patient-matched baseline tumors." (PMID 35525274, 2022). "In addition, YAP was also observed to play an important role in regulating the sensitivity of BRAF and KRAS mutant cancer cells to specific drugs, and the invasive activity of melanoma in vitro and in vivo." (PMID 35141161, 2022). "Considering that RASSF1A can promote apoptosis upon sustained KRAS activation, it would be worth investigating whether melanomas that rely on KRAS to survive could benefit from RASSF1A restoration to promote cell death." (PMID 34066022, 2021). "Additionally, the combination of CDK4 and MAPK pathway inhibitors has shown tumor regression in xenograft models of cancers with KRAS, NRAS, or BRAF mutations, particularly BRAF- and NRAS-mutant melanoma, with promising results from phase I clinical studies." (PMID 34309585, 2021). "However, we identified six KRAS mutations and one NRAS mutation in 19 melanomas of the female genital tract." (PMID 34102999, 2021). "Polymerase Chain Reaction (PCR) and Sanger sequencing techniques were performed to identify the mutational status of BRAF, NRAS, KRAS, NF1, KIT, PDGFRA and SF3B1 on 19 melanomas of the female genital tract, paired with 25 cutaneous melanomas, 18 acral melanomas and 11 melanomas of nasal cavity." (PMID 34102999, 2021). "Additionally, recurrent KRAS and KIT mutations occurred predominantly in polygonal and epithelioid cell types of melanoma in the female genital tract." (PMID 34102999, 2021). "Since KRAS mutations are rare in melanoma, no results are available for immunotherapy outcome in this group." (PMID 34072863, 2021). "As expected, KRAS mutation dependence was observed in colon, pancreatic and lung cancer cell lines, NRAS mutation dependence in melanoma lines, and BRAF mutation dependence in colon, thyroid and melanoma lines." (PMID 34254730, 2021). "Interestingly, the recurrent KRAS and KIT mutations occurred predominantly in polygonal and epithelioid cell subtypes, but rarely in spindle cells, in melanoma of the female genital tract." (PMID 34102999, 2021). "In all melanomas, real-time PCR did not disclose any BRAF mutation; melanoma #1 was KRAS and NRAS (lesions #2, 3, 4) wild type." (PMID 33614203, 2021). "A novel RAF inhibitor, LXH254—which may have activity in tumors with concurrent BRAF and NRAS mutations, and in melanoma cell lines that are resistant to BRAF and MEK inhibition—was found to be less active in the KRAS mutant cell lines." (PMID 34830283, 2021). "Recent work has shown that inhibition of wild-type KRAS in BRAF-mutant melanoma can be a potential strategy since inhibition of KRAS works synergistically with BRAF inhibition to reduce the proliferation and induce apoptosis independent of BRAF mutation status." (PMID 33801965, 2021). "The most prevalent significantly mutated genes in melanoma such as BRAF, NRAS, KRAS, HRAS, and NF1 were also explored; the results indicated that the high-FRGs score group have lower mutation frequencies in NRAS, KRAS, and NF1 compared to the low-FRGs score group." (PMID 34745259, 2021). "In addition to HRAS and KRAS, we also computationally identified several significantly mutated genetic interactions for new gene families, such as SEPT1-BRIP1 in melanoma." (PMID 32101536, 2020).
melanoma (continued). "Therefore, it is of importance that also in melanoma the miR-622-target KRAS was shown by our group to strongly affect BRAF-inhibitor resistance." (PMID 31906510, 2020). "In another study, KRAS was shown by our group to be majorly regulated by miR-622 in melanoma." (PMID 31906510, 2020). "In summary, miR-622 exhibits potent tumor-suppressive functions in HCC and in melanoma via affection of several relevant target genes and mechanisms, respectively, with KRAS being the major target responsible for miR-622’s inhibitory effect on HCC proliferation and clonogenicity." (PMID 31906510, 2020). "The frequency of mutations in the genes is consistent with that reported in the literature for IDH1 and IDH2 in brain tumors, EGFR and KRAS in NSCLCs, KRAS and NRAS in CRCs, BRAF, RAS, PIK3CA, and TERT in thyroid nodules, BRAF, NRAS and cKIT in melanoma, and KRAS in pancreatic pre-operative samples." (PMID 32340363, 2020). "KRAS/c-MYC dysregulation increases melanoma NC toxicity reversed by TTM." (PMID 30792807, 2019). "Kirsten rat sarcoma viral oncogene homolog (KRAS)and Harvey rat sarcoma viral oncogene homolog (HRAS) may also be mutated in melanoma, but only in a very small percentage of cases (~1%)." (PMID 30987166, 2019). "In the advanced search mode with restrictions of ‘melanoma’ and ‘KRAS’, 12 entries were retrieved." (PMID 31819989, 2019). "In agreement with what has been observed in melanoma patients, we found that the dominating mutation in this cell line panel was BRAFV600E/K (34 of 49), whereas other mutations in BRAF, NRAS, or KRAS were less common (5/49, 8/49, and 1/49)." (PMID 31253656, 2019). "KRAS/c-MYC dysregulation attenuates TTM reversion of melanoma toxicity by DSF + OPT." (PMID 30792807, 2019). "In this study BRAF, NRAS, KRAS, HRAS, PIK3CA and KIT mutations were examined in melanomas." (PMID 31277584, 2019). "During expansion, a PR occurred in 2 patients with BRAF-mutated melanoma (1 KRAS-WT and 1 of unknown KRAS status) and 1 with BRAF-WT, KRAS-WT melanoma; all three received E6201 320 mg/m2 once-weekly." (PMID 29867224, 2018). "BAY 1238097 is a new BET inhibitor that has been tested against lymphoma and, more recently, melanoma, but its use against KRAS-mutated tumors has not been yet investigated." (PMID 29721157, 2018). "TIBs bearing KRAS-specific BCRs could represent the cross-activation of the humoral immune response in patients with KRAS-mutant cancer the same way as the NY-ESO-1 paradigm in melanoma." (PMID 30283732, 2018). "We further classified the 89 samples into the four molecular subtypes, BRAF mutated (47% in melanoma TCGA), RAS mutated (NRAS/KRAS/HRAS mutations, 29%), NF1 mutated (9%), and Triple-WT (subgroup lacking above mutations, 15%), proposed by the recent TCGA melanoma cohort." (PMID 30373548, 2018). "Moreover, the treatment with LY3009120 inhibited the growth of melanoma cells that harbor NRAS mutations xenografts and KRAS-driven colorectal tumors in vivo." (PMID 29455659, 2018). "KRAS mutations have not been assessed in most previous studies of mucosal melanoma, however, accounted for one third of the mutations in RAS genes observed in our cohort." (PMID 28380455, 2017). "Although it is not clear why NRAS mutations are more frequent in melanoma compared to HRAS or KRAS mutations, there is evidence that NRAS is overexpressed in melanocytes relative to other RAS isoforms." (PMID 29349077, 2017).
melanoma (continued). "Interestingly, IPA3 specific PAK inhibitor is able to inhibit the proliferation of melanoma and CRC cells with mutations at KRAS or NRAS better, than those containing mutations at BRAF." (PMID 25361007, 2014). "In addition, RAS mutations (HRAS, KRAS, or NRAS) have been identified in ∼55–60% of thyroid cancers, and BRAF mutations have been identified in ∼60% of malignant melanomas." (PMID 23991070, 2013). "Other studies also reported that NRAS mutations were detected in ∼10–25% of melanomas and KRAS mutations were detected in ∼30% non-small cell lung cancers (NSCLCs)." (PMID 23991070, 2013). "Second, the singular focus on KRAS-centric pathways, although justified by emerging evidence of KRAS involvement in some melanomas, may overlook synergistic or compensatory signaling through parallel oncogenic axes such as those governed by BRAF, NRAS, or PI3K-AKT-mTOR." (PMID 40607411, 2025). "In addition to a potential lineage association, oncogenic KRAS signaling is the best predictor for a tumor suppressive role of AMBRA1 in LUAD, and oncogenic BRAF signaling correlates with AMBRA1 tumor suppressive activity in melanoma in DepMap." (PMID 39617889, 2024). "Patient #27, indeed, had multiple recognized melanoma drivers including BRAF p.V600K, RAC1 p.P29S, pTERT C228T and KRAS p.G12A, this latter arising at the time of progression; thus, patient #27 represents a good example of a combined intrinsic (RAC1 mutation) and acquired (KRAS mutation) resistance." (PMID 38548846, 2024). "In addition, the subgroup of melanoma cases with high expression of both SOX2 and GLI1 exhibited lower frequency of KRAS mutations (0.0182 vs. 0.292) and higher frequency of PTEN mutations (0.1272 vs. 0.0414), although the relevance of this finding needs further investigation." (PMID 33958721, 2021). "In a recent study the authors found that together with KRAS and galectin 3, melanoma cells could induce a stem-like phenotype and resistance to chemotherapeutics via a TBK1 activated NFκ-B signalling pathway, which is involved in the activation of inflammation." (PMID 34439879, 2021). "Furthermore, acquired resistance to BRAF inhibitors in melanoma was dependent on dynamic regulation of KRAS expression and could be overcome by KRAS inhibition." (PMID 31906510, 2020). "Therefore, role of KRAS signaling in melanoma must be evaluated." (PMID 32934956, 2020). "Interestingly, one melanoma which developed a novel NRAS non-hot-spot mutation p.(P140S) predicted by in silico approach to be benign also carried a pathogenic hot-spot KRAS mutation p.(G12C)." (PMID 31745173, 2019). "Thus, in melanoma, one sample (6.2%) had an uncommon BRAF (c.1400C>T; p.Ser467Leu) mutation, one (6.2%) had an NRAS (c.385C>T; p.Gln129*) mutation, and rare EGFR, ERBB2, KRAS, and MET mutations were also exhibited in one sample (6.2%)." (PMID 28404952, 2017). "While initially used with melanoma, ACT strategies have more recently been extended to several cancer types, including KRAS-mutant tumors." (PMID 41309533, 2025). "The interplay between NRAS, KRAS and HRAS in the context of NRAS-mutant melanoma and other tumor types remains poorly understood." (PMID 40473796, 2025). "Lastly, the well-established oncogenes KRAS and MYC were also identified within melanoma-derived EV, supporting a potential role for EV-mediated transfer of these tumorigenic factors in promoting malignant transformation and tumor progression." (PMID 40805206, 2025). "One tumor with an NRAS G12R mutation had an intrachromosomal chromothripsis event spanning KRAS, while BRAF and NF1 were involved in chromothripsis events in one NRAS melanoma each." (PMID 38758740, 2024). "The clinically characterized tumor molecular subtypes included BRAF, NRAS, KRAS, KIT, and PIK3CA mutant melanomas, with BRAF mutant melanomas being more prevalent in AYA compared to adult patients (77% vs 41%; Fisher’s exact test, P = 0.0003)." (PMID 38589406, 2024).
melanoma (continued). "Whereas, reflex NGS testing with an expanded panel also encompassing KRAS, KIT, and NRAS is only limited to ocular and mucosal melanomas." (PMID 39661469, 2024). "Molecular testing for common melanoma driver genes, including BRAF, NRAS, KRAS, HRAS, NF1, and KIT, was available for this study." (PMID 37686691, 2023). "Class 2 BRAF mutations were also significantly more prevalent in HRAS (8%) compared to KRAS- and NRAS-mutant melanoma." (PMID 37503077, 2023). "These cell lines, which included a range of cancer types (lung, melanoma, or breast) and oncogenic drivers (KRASG12S, BRAFV600E, and PTEN, respectively), showed accumulation of NRAS and KRAS under MEKi treatments." (PMID 37370689, 2023). "Results from selected completed clinical trials investigating MEK inhibition as part of dual and triple therapy regimens in patients with KRAS-/BRAF-mutant solid tumors and melanoma." (PMID 35965494, 2022). "High EGFR promotes RAFi resistance in CRC, lung, melanoma and thyroid cancer cells by rapid feedback activation of EGFR signaling 113-117, and determines the G12Ci refractory state in KRAS G12C cancers 33, 34, 118-120." (PMID 35966590, 2022). "The CE-IVD labels for Idylla molecular assay are assigned only to specific tumor types for each assay-NSCLC for EGFR; CRC for KRAS, NRAS-BRAF and MSI, and melanoma for BRAF." (PMID 36293374, 2022). "A growing of literature has documented that the NRAS mutation is substantially related to a higher incidence of melanoma (i.e., 15–30% of melanoma), which is ten times higher than repeatedly than HRAS or KRAS." (PMID 36551688, 2022). "For example, Ro-4987655, a highly selective mitogen-activated protein kinase kinase (MEK) inhibitor, has proved its efficacy in BRAF V600 mutant melanoma, BRAF wild-type melanoma, and KRAS mutant NSCLC patients." (PMID 34603309, 2021). "These genomic subtypes include BRAF-mutant melanoma (50%), NRAS, KRAS and HRAS-mutant melanoma (25%), NF1-mutant melanomas (15%) and triple wild-type melanomas (10%)." (PMID 34572747, 2021). "KRAS aberrations are mainly found in lung, pancreatic and colon cancer, NRAS in melanoma and HRAS in bladder and head and neck squamous cancers." (PMID 32560574, 2020). "For example, NRAS is the most common in melanoma, while HRAS in adrenal glands and KRAS in pancreas." (PMID 31941155, 2020). "RAS proteins including the isoforms KRAS and NRAS are amongst the most prominent oncogenes and were recently described to play major roles also in melanoma and HCC." (PMID 31906510, 2020). "We focused our attention on EGFR, BRAF, KRAS, and BRAF genes for NSCLC, melanoma, and mCRC samples, respectively." (PMID 32054005, 2020). "This was evidenced for KRAS wild-type squamous cell carcinomas that acquired resistance to cetuximab and proofed for BRAF (V600E)-mutant melanoma cells that became resistant to vemurafenib." (PMID 31948066, 2020). "Such involvement of DRP1 in tumorigenic potential and metabolic reprograming downstream of KRAS/BRAF is supported by some previous studies in separate models of PDAC and melanoma." (PMID 33738242, 2020). "Dual MAPK pathway inhibition (dabrafenib and trametinib) was proven to have strong anti-tumor activity and good safety profile in patients with BRAF-mutant melanoma brain metastases, BRAF-mutant NSCLC, and KRAS-mutant-positive NSCLC." (PMID 31652660, 2019). "We used the peptide conjugates to treat the B-Raf inhibitor resistant MM415 (human malignant melanoma, BRAF wt, KRAS wt, NRAS Q61L) cell line." (PMID 30909892, 2019).